FADD (Fas associated via death domain)
Diseases named in the same sentence as FADD in open-access papers (continued):
Sharing a sentence is not in itself a finding about the gene and the disease.
T-cell neoplasms (1 paper, 2022). "A significant reduction in Fas-associated proteins with death domain (FADD) levels has been reported in precursor T-cell neoplasms by our group and others." (PMID 36499482, 2022). "We reveal that reduced FADD levels are associated with poor prognosis in precursor T-cell neoplasms, and that such reductions determined a significant enrichment of oncogenic gene signatures, including resistance to chemotherapy." (PMID 36499482, 2022). "In this work, we explore the clinical significance of FADD expression in precursor T-cell neoplasms and the enrichment of distinctive genetic signatures in patients, according to FADD levels." (PMID 36499482, 2022). "Herein, we applied a DIA-MS-based proteomic method to screen specific protein interactions of endogenous FADD proteins in precursor T-cell neoplasm-derived JURKAT cell lines." (PMID 36499482, 2022). "This non-canonical function would be particularly relevant in precursor T-cell neoplasms where FADD is available." (PMID 36499482, 2022). "Altogether, our results point towards a dual role for FADD in precursor T-cell neoplasms, where FADD reduction would affect its canonical function, programmed cell death, leading to cell death resistance and subsequent chemotherapy resistance." (PMID 36499482, 2022). "We performed a disease-free survival analysis from 34 patients with a precursor T-cell neoplasm, which revealed significantly shortened disease-free survival for patients exhibiting low FADD expression." (PMID 36499482, 2022). "We performed in vitro analysis of cell cycle phase distribution in FADD-expressing (JURKAT-FADD) and FADD-deficient (JURKAT-NEG) precursor T-cell neoplasm-derived JURKAT T-cells, either in untreated cells or upon specific pharmacological treatments." (PMID 36499482, 2022). "The analysis of clinic-pathological parameters in the much larger TARGET cohort, consisting of 264 patients with a precursor T-cell neoplasm, revealed additional correlations between FADD expression and poor outcome factors." (PMID 36499482, 2022). "In silico analysis of whole transcriptomics data from the cohort of 264 patients with precursor T-cell neoplasm has allowed us to identify specific genetic signatures in patients with reduced FADD levels (FADD-negative phenotype)." (PMID 36499482, 2022). "To further investigate the implication of FADD expression in the outcome of precursor T-cell neoplasms, we performed additional analyses of the clinic-pathological data associated to 264 patients (TARGET cohort), considering FADD levels." (PMID 36499482, 2022). "We sought to explore the relationship between FADD expression and the landscape of deregulated cell signaling events in human precursor T-cell neoplasms." (PMID 36499482, 2022). "For such purpose, we analyzed disease-free survival of patients with a precursor T-cell neoplasm exhibiting differential FADD levels, followed by analysis of transcriptomic and clinical data from a cohort of 264 patients." (PMID 36499482, 2022). "We propose a dual role for FADD in precursor T-cell neoplasms, where FADD reduction would affect its canonical function, programmed cell death, leading to cell death resistance and subsequent chemotherapy resistance." (PMID 36499482, 2022). "In support of this notion, we also observed a significant association with gene signatures related to chemotherapy resistance in precursor T-cell neoplasms exhibiting reduced FADD levels." (PMID 36499482, 2022). "In this study, we set out to gain insight into the clinical implications of FADD expression, and to explore the landscape of dysregulated cell signaling events in human precursor T-cell neoplasms, taking FADD expression as the defining variable." (PMID 36499482, 2022). "A reduction in FADD levels has been reported in precursor T-cell neoplasms and other tumor types." (PMID 36499482, 2022).
T-cell neoplasms (continued). "In summary, these results reveal that evaluation of FADD expression in precursor T-cell neoplasms may aid in the understanding of the biological processes that are affected in the tumor cells." (PMID 36499482, 2022). "More recent studies by our group reported that FADD reduction might be a frequent mechanism whereby Fas-mediated apoptotic signaling would be affected in precursor T-cell neoplasms." (PMID 36499482, 2022). "Linking FADD expression to the severity of precursor T-cell neoplasms could indicate its use as a prognostic marker and may open new avenues for targeted therapeutic strategies." (PMID 36499482, 2022). "This may explain why precursor T-cell neoplasm patients with reduced FADD levels display genetic signatures of resistance to anti-cancer therapies." (PMID 36499482, 2022). "Since the ETP subtype is considered a very high-risk group and the Cortical subtype has shown the best clinical outcomes, these results indicate that FADD expression may have a prognostic value for precursor T-cell neoplasms." (PMID 36499482, 2022). "Furthermore, whether FADD expression has implications beyond the impairment of FADD-dependent programmed cell death is yet to be elucidated in human precursor T-cell neoplasms, thus representing a pertinent topic for cancer research." (PMID 36499482, 2022). "To do so, we performed bioinformatics analyses on whole transcriptional profiles of the 264 patients with precursor T-cell neoplasms (TARGET cohort), which revealed that patients exhibited different genetic signatures depending on FADD expression." (PMID 36499482, 2022). "Furthermore, this implies that FADD may participate in pathogenic changes of energy metabolism in those precursor T-cell neoplasms that do not exhibit a phenotype of cell death resistance, and consequently a phenotype of resistance to chemotherapy due to FADD reduction." (PMID 36499482, 2022). "FADD preservation in tumor cells, however, would affect its non-canonical roles, and our results indicate that changes in energy metabolism is a relevant non-canonical function in precursor T-cell neoplasms." (PMID 36499482, 2022). "FADD preservation in tumor cells, however, would affect its non-canonical functions, and our results indicate that changes in energy metabolism are such a relevant non-canonical function in precursor T-cell neoplasms." (PMID 36499482, 2022). "However, increasing evidence indicates that FADD is also relevant for non-apoptotic functions in T-cells, meaning FADD expression in precursor T-cell neoplasms may involve further functional implications." (PMID 36499482, 2022).
testis tumor (1 paper, 2024). "Silencing of the Fas/FasL-driven death receptor pathway by transfection with dominant-negative FADD attenuated the cytotoxic effect of cisplatin in the 833 K testis tumor cell line, supporting again that activation of Fas/FasL signaling contributes to cisplatin sensitivity of testis tumor cells." (PMID 37891379, 2024).
Thrombocytopenia (1 paper, 2021). A reduction in the number of circulating thrombocytes. "We investigated the effects of the exposure of ABT-737, an apoptosis- and thrombocytopenia-inducing drug, on the expression of FADD and DJ-1 as well as on the caspase-8 activity in human platelets." (PMID 33428668, 2021).
thymic lymphoma (1 paper, 2024). "Additionally, FADD-deficient mice (FADD−/−) develop thymic lymphoma as they age." (PMID 38542202, 2024).
Thyroid adenoma (1 paper, 2005). The presence of a adenoma of the thyroid gland. "Using a mouse model of thyroid adenoma/adenocarcinoma, we showed spontaneous disappearance of FADD protein expression during the course of tumor development." (PMID 15717929, 2005). "In contrast, thyroid adenoma/adenocarcinoma expressed low or no FADD protein." (PMID 15717929, 2005). "However, FADD mRNA was normally expressed in mouse thyroid adenoma/adenocarcinoma and in human AML cells, and lack of FADD mRNA could not account for poor FADD protein expression in these cancer cells." (PMID 15717929, 2005).
tongue cancer (1 paper, 2016). A malignant neoplasm affecting the tongue. "The relationship between FADD expression and tumor differentiation was similar to that in early stage tongue cancer." (PMID 27764170, 2016).
ZIKV infection (1 paper, 2020). "Transcript levels of TRAILR2 (DR4) and adaptor protein FADD were also enhanced upon ZIKV infection." (PMID 33207682, 2020).
cancer (151 papers, 2005 to 2026). A tumor composed of atypical neoplastic, often pleomorphic cells that invade other tissues. "In cancer, loss of FADD inhibits apoptosis and induces tumor cell survival, making it a promising therapeutic option for treating cancer." (PMID 39859448, 2025). "Constitutive expression of FADD aids cellular homeostasis; however, defective or low expression of FADD has been implicated in pathological manifestations in different types of cancers." (PMID 38542202, 2024). "FADD overexpression was associated with the activation of several cancer-related pathways, such as the MAPK and MTOR signaling pathways." (PMID 38684755, 2024). "Our findings indicate that sensitivity to UNE-C1-induced cell death is dependent on the expression levels of TLR2 and the Fas-associated death domain (FADD) in cancer cells." (PMID 39669578, 2024). "By connecting to the death receptors (DR-4 and DR-5), TRAIL induces cancer cell death by assembling a death-inducing complex consisting of FADD (Fas Associated Via Death Domain) and caspase-8." (PMID 36769263, 2023). "In other studies, FADD activity has also been found to be associated with the immune escape mechanism of cancer cells." (PMID 37671047, 2023). "FasL, expressed on activated T cells and natural killer (NK) cells, poses another way to kill cancer cells by recruiting Fas-associated protein with DD (FADD) and activating caspase pathways." (PMID 35646685, 2022). "Altogether, this highlights the notion that resisting programmed cell death, which is a hallmark of cancer, would be a canonical consequence of FADD deficiency in these tumors." (PMID 36499482, 2022). "FADD dysregulation has been shown to be closely associated with the pathogenesis of numerous types of cancer." (PMID 36348274, 2022). "The release of FADD increased significantly with the cancer stage, and was associated with both early and late steps of the metastasis process." (PMID 36348274, 2022). "We performed time-lapse microscopy experiments on BioStation to study changes of cellular morphology of WT cells and CASP3/7/6- and FADD-deficient cells during long-time period of treatment (96 h) with selected anti-cancer drugs (Campt, Taxol, and Eto)." (PMID 33800107, 2021). "Collectively, these results show that the most resistant cell lines to anti-cancer drug treatments are FADD-, CASP3/7/6-, and CASP3/7-deficient cells." (PMID 33800107, 2021). "In our analyses, only marker rs4197 (FADD gene) was associated to GC development as follows: INS/DEL genotype of rs4197 increasing in about 2-fold the chances of developing this type of cancer (P = 0.046; OR = 1.940; 95%CI = 1.011–3.725)." (PMID 33076854, 2020). "Amplification of the 11q13, a chromosomal region containing the gene encoding FADD, is frequently observed in many cancer cells." (PMID 27013580, 2016). "Recently, FADD has also been implicated in tumorigenesis and is frequently amplified in many cancer cells, acting as a biomarker." (PMID 27286445, 2016). "Induction of apoptosis by CFZ occurs, at least in part, due to activation of the extrinsic apoptotic pathway, since FADD deficiency protected cancer cells from undergoing apoptosis." (PMID 26009898, 2015). "The role of the FADD adaptor in cancer was initially demonstrated by generating RAG-1 deficient transgenic mice that target expression of a FADD dominant negative mutant in lymphocytes." (PMID 15717929, 2005). "In cancer, loss of FADD inhibits apoptosis and induces tumor cell survival." (PMID 39859448, 2025). "Importantly, the mechanistic significance of FADD in cytoplasmic to nuclear trafficking is mostly associated with distinct cell and cancer types." (PMID 38542202, 2024).
cancer (continued). "This suggests that in those precursor T-cell tumors that are able to execute FADD-dependent programmed cell death, FADD may have a role in a different hallmark of cancer, deregulation of the cellular metabolism." (PMID 36499482, 2022). "Nevertheless, fully understanding the underlying mechanisms of FADD in the modulation of cancer-related signaling pathways may provide new insights into the development of effective therapeutic strategies for cancer patients." (PMID 36348274, 2022). "This suggests that resisting programmed cell death, which is the canonical function of FADD, could represent a major hallmark of cancer in these patients with reduced FADD levels." (PMID 36499482, 2022). "Indeed, there are reports which directly linked decreased level of phosphorylated FADD to poor clinical outcomes in cancer, which support 101-3p’s role as an oncomiR." (PMID 35096570, 2021). "The binding of DR5 to TRAIL recruits Fas-associated death domain (FADD) to the cytoplasmic part of DR5 in cancer cells, after which FADD interacts with procaspase-8, forming the death-inducing signaling complex (DISC), which activates the caspase pathway to induce cell apoptosis." (PMID 32548715, 2020). "A previous study showed that FADD played a role in regulating most of the signalosome complexes, causing it to emerge as a newly identified actor in innate immunity, inflammation, and cancer development." (PMID 32738922, 2020). "Furthermore, we revealed that the reactivation of AFP during hepatocarcinogenesis causes cancer cells to escape Fas/FADD-mediated apoptosis." (PMID 33009373, 2020). "Since HIF-1α is overexpressed in many cancers and has been associated with tumor aggressiveness and poor prognosis, it could be speculated that FADD downregulation would be involved." (PMID 31569512, 2019). "Particular studies confirm that FADD mutation is indeed a rare event in cancer." (PMID 31569512, 2019). "Mutations in FADD that are associated with cancers have also been shown to interfere with the association of FADD with MYD88, which may in turn promote myddosome assembly." (PMID 31131275, 2019). "Interestingly, cancer cell-specific FADD deletion was also associated with decreased myeloid infiltrates." (PMID 28212753, 2017). "However, some cancer cells upregulate TRAIL-R expression, and we recently showed that this facilitates progression of KRAS-mutated cancers via cancer cell-autonomous Rac1 activation independently of FADD." (PMID 28212753, 2017). "Changes in FADD expression and post-translational modification in cancer might be cell type-specific, thus resulting either in loss of apoptosis or gain of non-apoptotic functions." (PMID 27556297, 2016). "The selective anticancer efficacy of dandelion root extract has been attributed to its ability to induce death-receptor mediated extrinsic apoptosis in cancer cells selectively, and a loss of this activity was observed in cells with a dominant negative Fas-Associated Death Domain (FADD)." (PMID 25883673, 2015). "Silencing of MMP2 causes cancer cell apoptosis by up-regulating Fas/Fas-L and FADD." (PMID 23936390, 2013). "However, further research is required to elucidate the underlying mechanisms of FADD involved in cancer progression, which may be of great benefit to the development of FADD-based therapeutic strategies for cancer patients." (PMID 36348274, 2022). "Therefore, whether FADD is involved in the regulation of intrinsic apoptosis during cancer progression and the underlying mechanisms involved in this process should be further investigated in future studies." (PMID 36348274, 2022). "Therefore, further studies on whether FADD promoter hypermethylation is a frequent event leading to FADD reduction, particularly in cancer, where resistance to apoptosis is a hallmark, would be of interest." (PMID 31569512, 2019).